CTLA4 (cytotoxic T-lymphocyte associated protein 4)
Diseases named in the same sentence as CTLA4 in open-access papers (continued):
Sharing a sentence is not in itself a finding about the gene and the disease.
tumor (continued). "ICIs, including monoclonal antibodies against PD-1 (Pembrolizumab, Nivolumab), PD-L1 (Atezolizumab, Durvalumab, Avelumab), and CTLA-4 (Ipilimumab), have generated durable responses across many tumor types." (PMID 34631532, 2021). "Here, we report the first effort to combine conventional dose rate MRT with anti-CTLA-4, which resulted in ablation of the tumor in half of the mice, and activation of a prolonged antitumor immune response." (PMID 35008319, 2021). "The role of CTLA-4 in tumor cells is controversial, and a previous study suggests that elevated CTLA-4 expression in tumor cells of NSCLC is predictive of a good outcome." (PMID 34526987, 2021). "Inhibitory immune checkpoint axes such as PD-1/PD-L1 or B7/CTLA-4 thwart anti-tumor immune responses by suppressing cell mediated cytotoxicity against tumor cells." (PMID 33916348, 2021). "Various studies have shown that the blockade of immune checkpoints (PD/PD-L1 and CTLA-4) rescues TILs from tumor-induced glucose restrictions and restores glycolysis in T-cells." (PMID 34268109, 2021). "This combination regimen results in decreased levels of myeloid-derived suppressor cells (MDSC), splenic and intratumoral checkpoint-expressing T cells (PD-L1, LAG-3 and CTLA-4) and therefore positively modulates the tumor microenvironment." (PMID 33870463, 2021). "Plasma membrane receptors such as the Programmed Death 1 (PD-1) and the Cytotoxic T lymphocyte antigen 4 (CTLA-4) are responsible for the T cell anti-tumor suppression activity, leading to tumor escape from the immune surveillance." (PMID 33777750, 2021). "Ipilimumab and pembrolizumab have been extensively employed as immune therapies in clinic against tumor, targeting on CTLA-4 and PD-1 signaling, respectively." (PMID 33791390, 2021). "comparing neoadjuvant versus adjuvant regimens of anti–PD-1 plus anti–CTLA-4 found a greater expansion of tumor-resident T-cell clones in the peripheral blood of patients enrolled on the neoadjuvant arm." (PMID 35070956, 2021). "More recently, immune-checkpoint blockade targeting cytotoxic T-lymphocyte-associated protein 4 (CTLA-4), programmed death-ligand 1 (PD-L1), or programmed death-1 (PD-1) improved survival in both of these tumor types." (PMID 34940094, 2021). "When these were co-administered with a CTLA4 inhibitor, not only did that lead to tumor burden decrease but also to CD8+ T-cell mediated cytotoxicity on the Purkinje cells." (PMID 33897597, 2021). "Accordingly, Ipilimumab, a recombinant human IgG1 monoclonal antibody to blockade CTLA-4, was developed to boost patents’ immunity to eliminate tumor cells." (PMID 34095145, 2021). "Hypoxia has been shown to induce PD-1 and CTLA-4 selectively upregulated in the tumor microenvironment." (PMID 34282207, 2021). "We also showed that miR-138 can target multiple immune checkpoint molecules such as CTLA-4 and programmed cell death protein 1 (PD-1) to inhibit tumor-infiltrating Tregs." (PMID 34532286, 2021). "After cryotherapy tumour antigens, the immune system’s primary stimulated with anti-CTLA-4, and anti-PD-1 resulted in a robust cytotoxic CD8+ T-cell response with a potential systemic effect." (PMID 34281259, 2021). "For example, neoantigen signature in tumours correlated well with overall survival in patients undergoing anti-CTLA-4 treatment." (PMID 33923305, 2021). "The administration of anti-CTLA-4 alone delayed tumor growth compared to the control and increased survival time to 68 days but did not lead to cure." (PMID 33411055, 2021). "For example, CD4+ naive T cells (cluster 0/cluster 2) located at the core of the tumor expressed more immune checkpoint molecules, such as CTLA4, LAG3, HAVCR2, and TNFRSF9/CD137." (PMID 34513820, 2021). "This serves as the rationale for using anti-CTLA-4 antibodies such as ipilimumab and tremelimumab that block this interaction as a means of cancer immunotherapy, aiming to enhance anti-tumor immune responses." (PMID 34141625, 2021).
tumor (continued). "This strategy has been shown to be effective in a large number of tumours, as evidenced by the success of CTLA-4 (cytotoxic T-lymphocyte antigen 4) and PD-1 (programmed cell death protein 1) pathway-blocking antibodies." (PMID 33925214, 2021). "In particular, the use of cytotoxic T lymphocyte antigen 4 (CTLA4), programmed cell death 1 (PD-1), and programmed cell death 1 ligand 1 (PD-L1) inhibitors in the clinic has become a landmark breakthrough in tumor immunotherapy." (PMID 34326876, 2021). "Human tumor expression of CD47 has been shown to correlate with the expression of various co-inhibitory markers, such as program cell death protein 1 (PD-1) and cytotoxic T-lymphocyte associated protein 4 (CTLA-4), on tumor-infiltrating CD4+ and CD8+ T cells." (PMID 34603322, 2021). "Next, we used the 4T1 tumor xenograft model and performed an anti-CTLA4 immune checkpoint blockade treatment in the presence/absence of ES-072." (PMID 33879767, 2021). "Whilst the action of anti-CTLA-4 on effector T cells (Teffs) appears to be mandatory for immune control of the tumor, therapeutic leverage of CTLA-4 blockade on TME Tregs allows for deeper responses than those observed under blockade of CTLA-4 on Teffs alone." (PMID 33602280, 2021). "By contrast, a combinatorial regimen of IRE followed by anti-CTLA-4 therapy led to complete tumor regression in nearly half (46%; 7/15) of mice." (PMID 34162858, 2021). "On the other hand, the depletion of fibroblast activation protein (FAP)+ CAFs reduced the tumor growth and improved the efficacy of anti-CTLA-4 and anti-PD-L1 in KPC GEMM." (PMID 34290984, 2021). "CTLA-4 is transferred from intracellular vesicles to the cell surface after environmental stimulation and plays a role in sustaining the inhibitory tumor environment." (PMID 34526987, 2021). "We here reported that the EOMES gene was down‐regulated and contributed to highly expressed PD‐1 and CTLA4 in tumour‐infiltrated T cells." (PMID 33325636, 2021). "They found that the spheroids retained autologous tumour infiltrating CD8+ T cells and that combination treatment with anti-PD-1 and anti-CTLA-4 antibodies promoted their expansion and increased tumour killing." (PMID 34771746, 2021). "Nevertheless, it is also important to consider the role of immune response suppressor cells or immune checkpoint pathways as targets to overcome the tumor-induced immunosuppression, such as MDSCs, Tregs, or both PD-1 and CTLA-4 pathways." (PMID 34572849, 2021). "Anagnostou and colleagues assessed biopsies of relapsed NSLC patients and observed a downregulation of key tumor antigens indicative of an anti-PD-1 and anti-CTLA-4 resistance." (PMID 34268109, 2021). "Recently though, the outcome for such patients has been improved by the introduction of novel checkpoint inhibitor therapies that target immune checkpoint receptors including CTLA-4, PD-1 and PD-L1, to promote anti-tumor immunity." (PMID 35069536, 2021). "This combination treatment with TA99, trametinib and ICB (with anti-PD1 or anti-CTLA4) mAb resulted in a significant reduction of tumor size compared to the control groups." (PMID 33520112, 2021). "Normally, CTLA-4 suppresses T cells in the early stages of the immune cycle in lymph nodes, while PD-1 regulates the immune response in peripheral tissues or tumor sites 21,23." (PMID 33531977, 2021). "Like human tumors, KPC tumor-bearing mice are mostly refractory to ICIs, including anti-PD-L1/PD-1 and anti-CTLA-4 antibodies." (PMID 33503832, 2021). "Many tumor types, including CRC, overexpress the immune checkpoint cytotoxic T-lymphocyte-associated protein 4 (CTLA-4) and thus transmit inhibitory signals to T cells." (PMID 33477757, 2021). "This revealed that the majority (>95%) of these expanded SPAS-1+ T cells in the IRE+ anti-CTLA-4 condition were in the tumor IV-neg gate and therefore concentrated in the tumor." (PMID 34162858, 2021).
tumor (continued). "Most recently, co-operation between IL-36 and anti-CTLA-4 mAbs has been observed to enhance tumour eradication and reduce lung metastasis as compared to CTLA-4 mABs alone." (PMID 34365521, 2021). "Checkpoint blockade therapy using anti-PD-1 and anti-CTLA-4 based drugs to inhibit tumor-mediated immunosuppression is proving to be a very powerful approach to treating some types of cancer." (PMID 33422137, 2021). "Our study suggests a correlation between the presence of tumor-infiltrating lymphocytes and CTLA4 promoter methylation." (PMID 33196890, 2021). "Tumor inhibition was significantly increased when co-administered with checkpoint inhibitors anti-CTLA-4 or anti-PD-1." (PMID 33803078, 2021). "They showed that miR-138 can educate CD4+ T cells by downregulating two immune checkpoints, programmed cell death 1 (PD-1) and cytotoxic T-lymphocyte-associated molecule 4 (CTLA-4), resulting in 43% increase in median survival time in GBM tumor bearing mice." (PMID 33911148, 2021). "When the antibodies bind to PD-L1/PD-1 or CTLA-4, the inhibitory effect is canceled and an immunological response against cancer cells starts by activation of tumor-reactive T cells." (PMID 33761971, 2021). "We are currently investigating the characteristics of an effective anti-tumor T cell response generated by radiation and anti-CTLA4 in mice." (PMID 34078406, 2021). "In fact, ADCC, which is mediated by macrophages in addition to NK cells, is an essential component of anti-tumor monoclonal antibody therapies, including those targeting CTLA-4, CD20, and HER2." (PMID 33564072, 2021). "Anti-CTLA4 antibodies can prevent the dysfunction of T cells and potentiate tumor-specific immune responses by blocking the activity of CTLA-4." (PMID 34367111, 2021). "CTLA-4 is highly expressed by tumor infiltrating HCC-specific CD8 T cells and the level of expression inversely correlates with the effector function." (PMID 33923463, 2021). "Compared with RT+L19–IL2, RT+anti-PD-L1 was therapeutically worse, while RT+anti-CTLA-4 or anti-PD-1 provided similar anti-tumor effects." (PMID 33688020, 2021). "Together, these findings suggest the therapeutic action of anti-CTLA-4 to rest mainly on pre-existing anti-tumor reactivity and to occur despite the on-treatment remodeling of the peripheral TCR repertoire rather than as a result of it." (PMID 33602280, 2021). "In particular, immune checkpoint blockades targeting PD‐1, PD‐L1, and CTLA4 have demonstrated promising clinical activity against several tumor types." (PMID 34240815, 2021). "Reliable evidence of synergistic effects from CTLA-4/PD-1 co-inhibition has been observed in clinical trials amongst other tumour types, in melanoma, renal cell carcinoma and NSCLC." (PMID 33757459, 2021). "Taken together, our data indicate that ARIH1 plays a role in promoting anti-tumor immunity, and that ES-072 is a promising agent to boost anti-tumor immunity and anti-CTLA4 immune checkpoint blockade immunotherapies." (PMID 33879767, 2021). "PD-L1 and CTLA-4 blockade was the most active approach, with 75% of long-term, tumor-free survivor mice even in the case of advanced or later-stage tumors." (PMID 33810532, 2021). "Ipilumumab is an anti-CTLA-4 monoclonal antibody and works by directly blocking CTLA-4, making way for downstream T cell activation, proliferation and eventual tumor destruction." (PMID 34200997, 2021). "In experiments studying populations of mice, the application of anti-CTLA-4 antibodies was found to improve the antitumor activity of gemcitabine by leading to sustained, long-term tumor size reduction." (PMID 34440813, 2021). "This CTLA-4 blocking strategy is expected to be widely used as an alternative for anti-tumor therapy due to the high prices of anti-CTLA-4 mAb drugs." (PMID 34525966, 2021). "For example, fRT, but not single-dose RT, induced an immune-mediated abscopal effect when combined with anti-CTLA-4 antibody in mouse tumor models." (PMID 33806808, 2021).
tumor (continued). "Several observations account for the functional relevance of this T cell subset in the mediation anti-CTLA-4 action on the tumor." (PMID 33602280, 2021). "PD-1 (PDCD-1) and CTLA-4 are important immune checkpoints that are responsible for tumor immune escape." (PMID 34754620, 2021). "In vivo focal irradiation of 4T1 tumours was shown to broaden the TCR repertoire with expansion of T cell clones driven by anti-CTLA-4 checkpoint inhibition." (PMID 34733287, 2021). "Treatment with anti-CTLA-4 or anti-CTLA-4 + GPB730 significantly inhibited tumor growth and enhanced survival compared to vehicle." (PMID 33786638, 2021). "In PC patients, miR-424–3p expression by in situ hybridization significantly correlated to CTLA-4 (p < 0.001) and PD-L1 (p = 0.040) immunohistochemical positivity of tumor cells." (PMID 34830196, 2021). "CD4+LAIR2+ cells highly expressed Treg cell lineage markers, including IL2RA, CTLA4, TNFRSF18, ICOS, TIGIT, and tumor-associated Treg cell marker CCR8, consistent with CD4+ LAIR2+ cells being of Treg lineage and not recently activated T cells." (PMID 35008369, 2021). "A similar fraction of mice that received resection + anti-CTLA-4 therapy also developed tumors although the tumor sizes trended smaller." (PMID 34162858, 2021). "The tumor cells or surrounding stromal cells secrete cytokines such as programmed cell death protein 1 (PD1) and cytotoxic T-lymphocyte-associated antigen 4 (CTLA4) to inhibit T cell functions." (PMID 34007747, 2021). "CTLA-4 blockade has demonstrated efficacy in anti-tumor immune activity in some cancers by allowing tumor antigen-specific T cell stimulation." (PMID 34631532, 2021). "Anti-tumor T cells are re-activated following the administration of the anti-CTLA-4 checkpoint blockade antibody." (PMID 34885172, 2021). "In this paper, we have investigated the combined effects of RT with the beta-emitting radionuclide lutetium-177 and CP immunotherapy using anti-PD-L1 and anti-CTLA-4 in an E0771 murine TNBC tumor model." (PMID 34063642, 2021). "Antibodies against the checkpoint proteins PD-1/PD-L1/2/CTLA-4 release this anti-tumor brake and reactivate protective T-cell activity." (PMID 33673374, 2021). "Again, the combination of BEMPEG and anti-CTLA-4 treatments with RT reduced tumor growth compared to BEMPEG and anti-CTLA-4 or RT alone (p<0.001)." (PMID 33937052, 2021). "Immune checkpoint inhibitors targeting the CTLA-4, PD-1, and its ligand PD-L1 have been successful at inducing an anti-tumor immune response in several cancers." (PMID 34268109, 2021). "Addition of elective nodal RT to immune checkpoint blockade using mAb and primary tumor RT decreased OS, mitigating the positive effects of anti-CTLA-4 mAb therapy." (PMID 34771432, 2021). "Anti‐CTLA4 delayed tumour progression as a monotherapy, and the combination of CTLA4 with CXD101 was similarly significant in the enhanced antitumour activity." (PMID 33773029, 2021). "Tumor immune checkpoint blockade immunotherapy targeting PD-1 or CTLA-4 prolongs the OS rate of cancer patients." (PMID 34956895, 2021). "In animal models, combination of CSF1R blockade and classical immunotherapy agents (as anti-PD1 and anti-CTLA4) has shown a reduced tumour growth compared to single treatment." (PMID 33627655, 2021). "CTLA-4 is a glycoprotein expressed on the T cell surface, which allows tumor cells to escape the immune system by binding to CD80/86 on APCs." (PMID 33920423, 2021). "This not only resists the access of T cells to intravasate into tumours even in the presence of CTLA-4 and PD-1 blockade, but also significantly impairs T cell activity." (PMID 33917287, 2021). "The positive association between stromal CTLA-4 and survival was explained by the presence of a TME in which anti-tumour immunity properties dominate." (PMID 35047074, 2021).
tumor (continued). "Although it is clear that CTLA-4 blockade can induce anti-tumor immunity with increased tumor infiltration of cytotoxic effector T cells, most studies do not account for any potential immunoregulatory contribution from the soluble isoform of CTLA-4." (PMID 35069536, 2021). "Studies 24 have shown that in the tumor microenvironment, anti-CTLA-4 stimulates the activation of surrounding T cells by blocking the binding of CTLA-4 on the surface of T cells to the ligand CD80/CD86 on APCs, but does not activate T cells." (PMID 33531977, 2021). "Immune checkpoint inhibitors (ICIs) targeting CTLA-4, PD-1, and PD-L1 proteins have revolutionized the treatment of melanoma and other tumor types in patients 1-4." (PMID 33391491, 2021). "Checkpoint blockade involves use of ICIs targeting immune checkpoint proteins, including PD-1 and CTLA-4 inhibitory receptors expressed by T cells, as well as PD-1 ligands 1 and 2 (PD-L1, PD-L2) expressed by stromal and tumor cells." (PMID 34716900, 2021). "The combination of CTLA-4 and PD-L1 inhibitors is believed to have the synergistic ability to overcome immune checkpoint resistance and induce anti-tumor activity." (PMID 33946408, 2021). "As expected, depleting CD8+ T cells using anti-CD8α mAb prevented tumor rejection on anti-CTLA-4 antibody treatment, indicating that ICI-mediated rejection of YTN16 was dependent on CD8+ T cell responses." (PMID 35008270, 2021). "Inhibitors targeting CTLA-4 and PD-1 block these inhibitory pathways, leading to reactivation of anti-tumor immunity and clinical benefit in some cancer patients." (PMID 34359674, 2021). "In vivo mouse models studying melanoma, ovarian and colon carcinoma showed higher tumor rejection rates and increased tumor induced lymphocyte activity and proliferation after combined therapy with CTLA-4 and PD-1 compared to monotherapy." (PMID 33802033, 2021). "Tumor cells within defined branch I in different tumors have upregulation of CTLA4 and CD80, indicating a better response to anti-CTLA4 therapy." (PMID 33971970, 2021). "It has been reported that ES occurs in patients receiving tumor vaccines, adoptive cell transfer therapy or anti-CTLA-4 treatment." (PMID 34732257, 2021). "Inhibitors targeting CTLA-4 have been shown to promote vaccine-induced tumor-specific T cell response directly by inhibiting such inhibitory signals." (PMID 34360800, 2021). "In murine tumor models, a key mechansism underlying the ability of radiation to induce local and systemic responses to anti-CTLA-4 in tumors resistant to anti-CTLA4 alone is the induction of IFN type I." (PMID 34078406, 2021). "Foxp3 and CTLA4 were downregulated, further contributing to a pro-inflammatory shift in the tumor microenvironment." (PMID 34688033, 2021). "CTLA-4 and PD-1, the most widely investigated checkpoints, are reportedly upregulated by the tumor to escape from immune system monitoring." (PMID 33717091, 2021). "In recent years, with widespread application of the immune checkpoint inhibitors PD-1/PD-L1 and CTLA-4, an increasing number of studies have been devoted to suppressing the progress of tumors by regulating the immune components in the tumor microenvironment." (PMID 34925511, 2021). "The combination of IL-33 with anti-PD-1 and anti-CTLA-4 antibodies further prolonged the survival of tumor-bearing mice." (PMID 34209038, 2021). "The two most heavily studied checkpoint inhibitor pathways in the tumor ablation field are CTLA-4 to CD80/86, blocking the normal co-stimulatory role of CD80/86 in T cell activation, and PD-1 to PDL1/2." (PMID 34136405, 2021). "ICI treatments, including therapies targeting PD-1, PD-L1, and cytotoxic T lymphocyte-associated protein 4 (CTLA4), have significantly benefited the survival of many types of tumor patients." (PMID 34771505, 2021). "The activation of EGFR is usually accompanied by upregulation of PD-1/PD-L1 or CTLA-4 to promote tumor immune escape." (PMID 34290608, 2021).